NKAIN3 (sodium/potassium transporting ATPase interacting 3)
Synonyms: FAM77D; FLJ39630; NKAIN3-IT1; UG0898H09
Tractability: Antibody: UniProt places it where antibodies can reach, with high confidence; UniProt predicts a signal peptide or a membrane-spanning region; its Gene Ontology location is reachable by antibodies, with medium confidence.
Gene: Protein-coding gene on chromosome 8 (62,248,591 to 63,014,000, forward strand). Ensembl gene ENSG00000185942.
Subcellular location: Cell membrane
Gene Ontology:
Biological process: regulation of sodium ion transport
Cellular component: plasma membrane
Genetic constraint (gnomAD): Loss-of-function variants: 7 observed, 9.01 expected, observed/expected ratio (o/e) 0.78, 90% interval 0.44 to 1.45. That is too few expected variants to judge how well the gene tolerates losing a copy. Missense variants: 103 observed, 119.99 expected, observed/expected ratio (o/e) 0.86, 90% interval 0.73 to 1.01. Synonymous variants: 44 observed, 45.43 expected, observed/expected ratio (o/e) 0.97, 90% interval 0.76 to 1.25.
Homologues: Orthologues: rat Nkain3 (95% identical), macaque NKAIN3 (93% identical), chimpanzee NKAIN3 (83% identical), dog NKAIN3 (82% identical), mouse Nkain3 (80% identical), guinea pig NKAIN3 (79% identical), pig NKAIN3 (78% identical), tropical clawed frog nkain3 (65% identical), Drosophila melanogaster NKAIN (39% identical), Caenorhabditis elegans gldi-7 (27% identical). Paralogues in human: NKAIN2 (57% identical), NKAIN4 (56% identical), NKAIN1 (54% identical).
Diseases named in the same sentence as NKAIN3 in open-access papers:
NKAIN3 is named in the same sentence as 11 diseases in open-access papers, as found by Europe PMC text mining. Sharing a sentence is not in itself a finding about the gene and the disease. The quoted sentences say what the papers report.
Dravet syndrome (2 papers, 2022). "An ATP6V0C de novo variant had been reported in a SCN1A-negative patient with Dravet syndrome while the patient simultaneously harbored de novo missense variants in the genes of NKAIN3 and SLC8A1." (PMID 35600075, 2022). "NKAIN3 encompasses a risk allele for dyslexia and is a known candidate gene for Dravet syndrome (MIM# 607208), which is a disorder characterized by an infantile-onset epileptic encephalopathy, intellectual disability, and refractory seizures." (PMID 36153334, 2022).
bulimia nervosa (1 paper, 2017). A disorder characterized by recurrent episodes of binge-eating over which the individual feels a lack of control; these episodes of binge-eating are followed by recurrent compensatory behavior to prevent weight gain, usually self-induced vomiting. "Previously, NKAIN3 has been reported in bulimia nervosa and taste perception of salt." (PMID 29187748, 2017).
Ciliopathies (1 paper, 2023). "Genes in state 3 were enriched for Ciliopathies, marked by NKAIN3 and CNBD1." (PMID 36929025, 2023).
narcolepsy (1 paper, 2020). A sleep disorder characterized by a tendency for excessive sleepiness during the day which occurs even after adequate sleep in the nighttime. "Located within the gene, the functions PPP2R2C, GPM6A, EPHX2, NKAIN3, ZNF365, TENM4, and PR2Y11 are related to narcolepsy." (PMID 32358372, 2020).
tumor (1 paper, 2012). "We also find two cases of inversions involving exonic material in NKAIN3 and TSPAN8, a cell surface antigen, which were found to be overexpressed in some human tumor cell lines." (PMID 23171647, 2012).
NKAIN3 also shares sentences with these, for which no sentence is quoted: dyslexia (1 paper); Epileptic encephalopathy (1); Infantile onset (1); Intellectual disability (1); neurologic disease (1); tobacco use disorder (1).